CHML (CHM like Rab escort protein)
Description:
Substrate-binding subunit (component A) of the Rab geranylgeranyltransferase (GGTase) complex. Binds unprenylated Rab proteins and presents the substrate peptide to the catalytic component B. The component A is thought to be regenerated by transferring its prenylated Rab back to the donor membrane. Less effective than CHM in supporting prenylation of Rab3 family.
Synonyms: REP-2; REP2
Tractability: PROTAC: ubiquitination databases record sites on it.
Gene: Protein-coding gene on chromosome 1 (241,628,851 to 241,640,369, reverse strand). Ensembl gene ENSG00000203668.
Subcellular location: Cytoplasm, cytosol
Subcellular location (Human Protein Atlas): Cytosol; Nucleoplasm
Pathways (Reactome):
Metabolism of proteins: RAB geranylgeranylation
Vesicle-mediated transport: RAB GEFs exchange GTP for GDP on RABs
Gene Ontology:
Molecular function: small GTPase binding; GDP-dissociation inhibitor activity
Biological process: protein geranylgeranylation; protein targeting to membrane; vesicle-mediated transport; intracellular protein transport; small GTPase-mediated signal transduction
Cellular component: cytosol; nucleoplasm; Rab-protein geranylgeranyltransferase complex; nucleus
Genetic constraint (gnomAD): Loss-of-function variants: 28 observed, 44.95 expected, observed/expected ratio (o/e) 0.62, 90% interval 0.46 to 0.85. The upper end of that interval is the gene's LOEUF score, 0.85, which puts it in group 3 of 6, group 1 being the genes least tolerant of losing a copy. Missense variants: 795 observed, 809 expected, observed/expected ratio (o/e) 0.98, 90% interval 0.93 to 1.04. Synonymous variants: 281 observed, 291.01 expected, observed/expected ratio (o/e) 0.97, 90% interval 0.88 to 1.07.
Homologues: Orthologues: dog CHML (86% identical), pig CHML (76% identical), mouse Chml (75% identical), rat Chml (74% identical), tropical clawed frog chm (57% identical), zebrafish chm (52% identical), Drosophila melanogaster Rep (28% identical), Caenorhabditis elegans rep-1 (27% identical). Paralogues in human: CHM (72% identical), GDI1 (19% identical), GDI2 (18% identical).
Diseases named in the same sentence as CHML in open-access papers:
CHML is named in the same sentence as 23 diseases in open-access papers, as found by Europe PMC text mining. Sharing a sentence is not in itself a finding about the gene and the disease. The quoted sentences say what the papers report.
choroideremia (7 papers, 2013 to 2025). Choroideremia (CHM) is an X-linked chorioretinal dystrophy characterized by progressive degeneration of the choroid, retinal pigment epithelium (RPE) and retina. "Interestingly, the ZIKV infection signature revealed the downregulation of ALDH5A1 and CHML, genes implicated in neurological (cognitive impairment, expressive language deficit, and mild ataxia) and ophthalmic (choroideremia) disorders, respectively." (PMID 30046058, 2018). "It has been hypothesized that relatively low expression of the homologous CHML gene in RPE cells could contribute to the eye-specific phenotype of choroideremia despite ubiquitous expression of CHM." (PMID 38920696, 2024). "A second isoform called REP-2, encoded by the gene CHML, is believed to compensate for the loss of REP-1 in most human tissues, except the eye, which could explain why choroideremia patients seems otherwise unaffected." (PMID 27685995, 2016). "REP family consists of only 2 members: choroideremia (CHM, REP1) and choroideremia-like (CHML, REP2)." (PMID 31175290, 2019). "Although the downregulation of CHML in iPSC-RPE cells may suggest that low CHML expression could contribute to choroideremia, CHML expression in the RPE or retina is not necessarily lower than in other tissues." (PMID 38920696, 2024). "In humans two REP homologues have been identified and while the consequences of REP‐2 (CHML) deficiency are not known, the deficiency of REP‐1 (CHM) leads to progressive retinal dystrophy – choroideremia." (PMID 34592024, 2021).
hepatocellular carcinoma (5 papers, 2019 to 2025). A malignant tumor that arises from hepatocytes. "Here, the authors show that expression of choroideremia-like (CHML) is elevated and associates with poor prognosis in hepatocellular carcinoma, and mechanistically CHML promotes metastasis in a Rab14-dependent manner." (PMID 31175290, 2019). "This notion is further supported by a recent study that indicated increased CHML levels play a role in promoting the progression of hepatocellular carcinoma." (PMID 35184380, 2022). "RAB14 recycling by CHML was shown to enhance cellular migration and invasion through improved trafficking of regulators of metastasis such as Mucin 13 and CD44 to the cell membrane in hepatocellular cancer." (PMID 36471277, 2022). "Choroideremia-like protein (CHML), a member of the Rab escort protein (REP) family, promotes migration, invasion and metastasis of hepatocellular carcinomas (HCC) cells by facilitating Rab14 recycling." (PMID 34868956, 2021).
liver cancer (3 papers, 2019 to 2025). An epithelial or non-epithelial malignant neoplasm that arises from the liver. "To further elucidate the molecular mechanisms underlying CHML-driven migration and metastasis in liver cancer, we conducted transcriptomic sequencing on CHML-knockout Huh7 cells." (PMID 40842592, 2025). "In this study, we observed that the expression of CHML in liver cancer tissues was elevated compared with that in normal tissues." (PMID 40842592, 2025). "To verify CHML’s role in tumor progression, we generated stable CHML-knockout Huh7 liver cancer cells using CRISPR-Cas9 and lentiviral transduction targeting exon 2, with PCR (500 bp band) and sequencing confirming mutations." (PMID 40842592, 2025). "To further explore the effects of CHML knockout on the occurrence and progression of liver cancer, we conducted a joint analysis of DEGs via transcriptomic sequencing and differentially metabolized compounds based on untargeted metabolomics." (PMID 40842592, 2025). "To determine CHML gene expression in liver cancer, we analysed data from the UALCAN database." (PMID 40842592, 2025).
lung adenocarcinoma (2 papers, 2022 to 2025). A carcinoma that arises from the lung and is characterized by the presence of malignant glandular epithelial cells. "Emerging evidence indicates that CHML, as a transcriptional target of NRF2, shows significant upregulation in lung adenocarcinoma and is strongly associated with poor prognosis." (PMID 40842592, 2025). "Analysis of patient data curated by The Cancer Genome Atlas (TCGA) and Oncomine databases revealed that CHML mRNA expression was elevated in lung adenocarcinoma (LUAD) patient tumor tissues and correlated with decreased patient survival." (PMID 35184380, 2022). "CHML levels are high in lung adenocarcinoma patients, correlating not only with increased expression of other NRF2 target genes, but also poorer prognosis and decreased overall patient survival." (PMID 35184380, 2022). "CHML overexpression correlates with poor prognosis in lung adenocarcinoma and multiple myeloma." (PMID 40842592, 2025). "This implies that the high levels of CHML observed in lung adenocarcinoma patients could be a key driver of both early and late stages of tumor progression." (PMID 35184380, 2022).
Ascites (1 paper, 2019). Accumulation of fluid in the peritoneal cavity (between the layers of the peritoneum that lines the abdomen). "Further analysis of CHML expression and clinicopathologic parameters revealed that high CHML expression was associated with serious ascites and more satellite nodules, and most importantly, earlier recurrence." (PMID 31175290, 2019).
ductal carcinomas (1 paper, 2007). "Majority of genes encoding proteins with enzyme activity or implicated in metabolism were also upregulated in ductal carcinomas (STK4, SLC1A2, B3GALT3, OSBPL10, CRBN, CHML, YWHAB)." (PMID 17389037, 2007).
Flavivirus Infections (1 paper, 2018). Infections with viruses of the genus FLAVIVIRUS, family FLAVIVIRIDAE. "Further studies are warranted to elucidate the function of the role of CHML in ZIKV and other flavivirus infections." (PMID 30046058, 2018).
influenza infection (1 paper, 2016). "We quantified the expression of four human mRNAs, two mRNAs that are significantly reduced during influenza infection (CHML and KIF18A, cluster 1) and two mRNAs that were less affected by infection (MYC and CDKN1B, cluster 3)." (PMID 27525483, 2016).
lung carcinoma (1 paper, 2022). "Of note is that Rep2 can also be increased in an NRF2‐dependent manner in breast and melanoma cancer cell lines, indicating that CHML could play a role in promoting cancers other than lung cancer." (PMID 35184380, 2022).
myeloma (1 paper, 2019). "High expression of CHML is associated with poor survival, which is related to cell proliferation and cell division of myeloma cells." (PMID 31762814, 2019). "Existing related studies have shown that the main role of CHML gene is to regulate the function of Rab protein, and it has also been reported that Rab protein can affect myeloma cells." (PMID 31762814, 2019). "So it is speculated that CHML may regulate the proliferation and division of myeloma cells by acting on Rab protein, but this needs to be further confirmed." (PMID 31762814, 2019). "This indicates that the CHML gene may be involved in the regulation of proliferation and division of myeloma cells in MM." (PMID 31762814, 2019). "CHML gene as a “detrimental gene” of MM may play a role in regulating the proliferation and division of myeloma cells." (PMID 31762814, 2019).
urothelial carcinoma (1 paper, 2019). A malignant neoplasm derived from the transitional epithelium of the urinary tract (urinary bladder, ureter, urethra, or renal pelvis). "This is consistent with the expression pattern of CHML gene in invasive urothelial carcinomas that highly expressed CHML is similarly indicates a low survival level." (PMID 31762814, 2019).
tumor (5 papers, 2019 to 2025). "In HCC, our prior collaborative work demonstrated that CHML escorts Rab14 to the membrane, sustaining Rab14 recycling to enhance tumor cell migration and invasion." (PMID 40842592, 2025). "Signal intensities in CHML KD group were much weaker than those in control group at 8 weeks after injection, which was consistent with less tumor foci in the livers in CHML KD group." (PMID 31175290, 2019). "Since high CHML expression predicted poor survival in clinic, we also evaluated the impact of CHML on survival of tumor-bearing mice in the intrahepatic injection model (n = 10 in control group and n = 12 in shCHML group)." (PMID 31175290, 2019). "Since Mucin13 and CD44 were well-known central players in tumor metastasis, we chose the two molecules to clarify the role of Rab14-positive vesicle in metastasis regulated by CHML." (PMID 31175290, 2019). "Besides, some genes which have close relationship with tumor metastasis such as choroideremia-like (CHML) and Insulin-like growth factor II mRNA-binding protein 3 (IMP3) are more abundant in satellite nodules." (PMID 38972883, 2024). "Therefore we examine the involvement of CHML in PVTT formation by analyzing the expression of CHML in paired tumor adjacent normal tissues, primary HCC tissues and PVTT tissues." (PMID 31175290, 2019). "Following CHML knockout or overexpression, we assessed the proliferative capacity of HCC cells using the Cell Counting Kit-8 (CCK-8) assay, 5-ethynyl-2′-deoxyuridine (EdU) incorporation, colony formation assay, and subcutaneous xenograft tumor models in nude mice." (PMID 40842592, 2025). "In vivo experimental results also demonstrated that CHML overexpression did not affect tumour volume or weight in nude mice relative to control tumours, indicating that CHML might not affect the proliferative ability of HCC cells." (PMID 40842592, 2025).
cancer (4 papers, 2019 to 2025). A tumor composed of atypical neoplastic, often pleomorphic cells that invade other tissues. "We conducted a pancancer analysis of CHML expression via the TCGA database and discovered that CHML was overexpressed in a variety of cancers." (PMID 40842592, 2025). "CHML is considered to help mature Rabs like CHM24, however, physiological function of CHML remains largely elusive, especially in cancer." (PMID 31175290, 2019). "Therefore CHML might promote cancer metastasis through metastasis regulators in Rab14-positive vesicles, and further studies were required to clarify the involvement of specific cargo proteins in the metastasis-promoting role of CHML–Rab14 axis." (PMID 31175290, 2019). "The function and evolution of these autosomal retrogenes derived from X-linked genes might be unrelated with MSCI during male meiosis and an explanatory example is that CHML, an ubiquitous expressed gene, has been reported to have function in cancer but not in reproduction." (PMID 34249105, 2021).
CHML also shares sentences with these, for which no sentence is quoted: infection (5 papers); adenovirus infection (1); Ataxia (1); cervical cancer (1); co-infection (1); Cognitive impairment (1); gout (1); multiple myeloma (1); viral infection (1); ZIKV infection (1).